AMH (anti-Mullerian hormone)
Diseases named in the same sentence as AMH in open-access papers (continued):
Sharing a sentence is not in itself a finding about the gene and the disease.
cryptorchidism (17 papers, 2015 to 2025). The failure of one or both testes of a male fetus to descend from the abdomen into the scrotum during the late part of pregnancy. "In a newborn or infant <6 months-old with cryptorchidism and micropenis, low serum AMH associated with low testosterone and gonadotrophins are strongly suggestive of congenital central hypogonadism." (PMID 38501100, 2024). "In patients with bilateral cryptorchidism, undetectable serum AMH and INHB suggest testicular tissue loss." (PMID 37152325, 2023). "Among the 11 cryptorchidism patients, three had mutations in either AMH or AMHR2, and these three patients were diagnosed with PMDS because pelvic MRI revealed the presence of Müllerian remnants." (PMID 35052499, 2022). "However, two cousins with an ANOS1 LOF variant and with a history of either untreated cryptorchidism, small testicular volume (<4 ml) but normal AMH and inhibin B levels had a good response to HCG treatment." (PMID 35432193, 2022). "This raises the question of how many cases with a simple bilateral inguinal cryptorchidism due to AMH/AMHR2 variants may be missed." (PMID 35432193, 2022). "Indeed, there is a high prevalence of cryptorchidism among subjects with mutations in AMH or AMHR2 (i.e., persistent Müllerian duct syndrome)." (PMID 31396156, 2019). "Nonetheless, serum AMH determination is a useful tool to assess the existence and functional capacity of testicular tissue during infancy, childhood and early puberty in boys with cryptorchidism, either isolated or associated with micropenis or with other signs of fetal undervirilization." (PMID 38501100, 2024). "For mammals with completely descended testes (CDT), cryptorchidism is a developmental defect that causes severe dysfunctions such as germ cell maldevelopment, asthenospermia, and imbalances in hormones such as testosterone (T) and anti-Müllerian hormone (AMH)." (PMID 33568072, 2021). "In boys with cryptorchidism, serum AMH levels reflect the mass of functional Sertoli cells: they are lower in patients with bilateral than in those with unilateral cryptorchidism." (PMID 38501100, 2024). "Since cryptorchidism is a sign of heterogeneous disorders, a wide range of serum AMH levels can be found in patients with undescended testes." (PMID 38501100, 2024). "In boys with cryptorchidism associated with micropenis, low AMH and FSH are indicative of central hypogonadism, and serum AMH is a good marker of effective FSH treatment." (PMID 38501100, 2024). "In boys with cryptorchidism, low serum AMH is suggestive of hypogonadism, reflecting a decreased Sertoli cell mass and, therefore, a reduced testicular size and/or an impaired Sertoli cell function." (PMID 38501100, 2024). "In a controlled clinical trial involving 54 participants, notable reductions in AMH and statin B levels were observed in boys with cryptorchidism." (PMID 39882265, 2024). "Specifically, among the cohort, the expression levels of AMH and statin B in 10 children with bilateral cryptorchidism decreased to more than twice that of the normal control group." (PMID 39882265, 2024). "Most studies have found that serum AMH is overall lower in boys with cryptorchidism than in the general population." (PMID 38501100, 2024). "In patients with cryptorchidism in the context of disorders of sex development, low serum AMH is suggestive of gonadal dysgenesis, whereas normal or high AMH is found in patients with isolated androgen synthesis defects or with androgen insensitivity." (PMID 38501100, 2024). "As expected, testicular AMH output is more affected in boys with bilateral undescended testes than in those with unilateral cryptorchidism." (PMID 38501100, 2024). "Nevertheless, a large study showed that serum AMH was clearly below the normal range in 16% of boys with unilateral cryptorchidism aged 1-6 months and in 7% of older infants and prepubertal boys." (PMID 38501100, 2024).
cryptorchidism (continued). "AMH is moderately decreased in cryptorchidism; even unilateral but still much higher than in females, an hCG test is not required." (PMID 33013698, 2020). "Further, boys with bilateral cryptorchidism have even lower levels of inhibin B and AMH compared to unilateral cases." (PMID 31396156, 2019). "The statistic parameters of UCH-L1, INSL3, AMH and inhibin B concentrations in plasma of children diagnosed with hernia and cryptorchidism." (PMID 29401475, 2018). "A measurable AMH in a boy who presented with bilateral cryptorchidism is predictive of undescended testes, while undetected AMH is suggestive of anorchia or the presence of ovaries as in cases of pure gonadal dysgenesis or female pseudohermaphroditism." (PMID 27532119, 2016). "In the management of young children with undescended testes, serum AMH measurement can be beneficial in assessing the gonadal function, reflecting the normal development of male genitals." (PMID 27532119, 2016). "Additionally, cryptorchidism impairs the functionality of Sertoli cells, which induces a low formation of AMH." (PMID 40043094, 2025). "Mean or median serum AMH is significantly lower (approximately -420 to -560 pmol/l, equivalent to -60 to -80 ng/ml) in boys with bilateral cryptorchidism than in age-matched controls, while a significant difference is not always evident between boys with unilateral cryptorchidism and controls." (PMID 38501100, 2024). "This implies that the secretion levels of AMH and statin B could serve as valuable indicators to guide the clinical management of children with cryptorchidism." (PMID 39882265, 2024). "The clinical utility of measuring serum AMH levels in boys with cryptorchidism will be discussed." (PMID 38501100, 2024). "Furthermore, significant variations in AMH levels were observed in cryptorchidism patients aged 2 years." (PMID 39882265, 2024). "The usefulness of serum AMH as a biomarker in patients with conditions that may present with cryptorchidism will be addressed in detail below." (PMID 38501100, 2024). "In boys with cryptorchidism, serum AMH increases after successful orchiopexy, indicating that the correction of the abnormal position may have a positive influence, even if partial, on testicular function." (PMID 38501100, 2024). "Low circulating levels of AMH may reflect primary testicular dysfunction, e.g. in certain patients with cryptorchidism, monorchidism, partial gonadal dysgenesis, or central hypogonadism." (PMID 27799946, 2016). "AMH and serum AMH concentrations may be useful biomarkers for the diagnosis of cryptorchidism." (PMID 36010553, 2022). "Anti-Mullerian hormone (AMH) is routinely used in the assessment of ovarian reserves and function, in the diagnosis of cryptorchidism and anorchidism, and in the evaluation of male gonadal functions at any age." (PMID 31782699, 2020). "Another study showed that serum AMH was normal in only half of the boys with cryptorchidism, without distinguishing between unilateral and bilateral forms." (PMID 38501100, 2024). "Paradoxically, in this regard, AMH assay is of little value because according to the gene involved, serum AMH can be either undetectable as in anorchia and CAH or normal or in the lower range of normal, as in cryptorchidism." (PMID 33013698, 2020). "These include anorchia together with very high gonadotropin levels and low/undetectable testosterone, AMH and inhibin B levels, or CHH presenting with cryptorchidism and small, but normally formed penis (i.e., micropenis) in the setting of very low gonadotropin and testosterone levels." (PMID 31396156, 2019). "In boys with bilateral cryptorchidism, AMH is low in approximately 75 % of those with non-palpable gonads and 35 % of those with inguinal gonads, indicating Sertoli cell dysfunction." (PMID 27799946, 2016).
cryptorchidism (continued). "Thus far, AMH levels appear to be useful in differentiating non-obstructive azoospermia from obstructive azoospermia, anorchidism from cryptorchidism, and constitutive pubertal delay from congenital hypogonadotropic hypogonadism in prepubertal males." (PMID 39032500, 2024). "Considering the absence of a history of cryptorchidism and the normal inhibin B and AMH levels, the child underwent a subsequent treatment with Follitropin alfa, which led to the enlargement of the testicular volume by 77% and the penile, but testosterone levels did not increase." (PMID 35432193, 2022). "Furthermore, as most PMDS patients were reported to carry genetic variants in AMH or AMHR2 gene, lack of differential diagnosis of cryptorchidism patients will increase the genetic risks in the second generation to a certain extent." (PMID 35052499, 2022). "The one cryptorchid dog in the present study had a SCT, so the effect of cryptorchidism on AMH concentration could not be established." (PMID 26209243, 2015). "However, AMH levels are not systematically decreased in all boys with cryptorchidism, and a few studies could not detect a significant difference as compared to control boys." (PMID 38501100, 2024).
COVID-19 (15 papers, 2021 to 2025). A disease caused by infection with severe acute respiratory syndrome coronavirus 2. "Given the variations in AMH assays and the need for cross-referencing other biomarkers, we studied the association of COVID-19 vaccination with AMH level and AFC among women seeking fertility treatment." (PMID 37326996, 2023). "Although AMH is widely used as a representative marker of ovarian function, studies on AMH alone to reflect the impact of COVID-19 vaccines on female reproductive capacity are far from sufficient." (PMID 40535340, 2025). "in March 2021 showed that women infected with COVID-19 had lower Anti-Müllerian hormone (AMH) levels, higher FSH levels, and higher levels of testosterone and prolactin than healthy women." (PMID 40535340, 2025). "Retrospective analysis from different angles was applied to investigate the effect of the inactivated COVID-19 vaccine on AMH levels among women." (PMID 40535340, 2025). "This study aimed to assess the impact of inactivated COVID-19 vaccine on Anti-Müllerian hormone (AMH) levels in Chinese women." (PMID 40535340, 2025). "Based on the present research findings, the general prevalence of menstrual and hormonal disorders, especially AMH and TSH levels were associated with COVID-19." (PMID 39906086, 2024). "In recovered COVID-19 women, choline was positively correlated with AMH (r = 0.48, p = 0.016), FSH (r = 0.51, p = 0.009), and progesterone (r = 0.51, p = 0.01)." (PMID 39125969, 2024). "According to a Chinese study, serum AMH levels in COVID-19 patients were significantly lower than those in healthy women." (PMID 38738039, 2024). "However, one study reported lower AMH levels among the COVID-19 recoverees and higher FSH levels, suggesting a smaller functional ovarian reserve." (PMID 36142911, 2022). "Therefore, the purpose of this study was to investigate whether the COVID-19 vaccination of inactivated vaccines in China would affect AMH in Chinese women, and thus indirectly assess whether it would affect ovarian function in Chinese women." (PMID 40535340, 2025). "Biochemically, post-COVID-19 participants demonstrated higher serum ferritin, estradiol, and fibrinogen levels, along with lower TSH and AMH levels, suggesting potential endocrine disruption and persistent inflammation." (PMID 40564856, 2025). "From a biochemical perspective, the post-COVID-19 group exhibited elevated ferritin, estradiol, and fibrinogen levels, along with reduced TSH and AMH levels." (PMID 40564856, 2025). "One original study demonstrated a decrease in anti-Müllerian hormone (AMH) levels and an increase in follicle-stimulating hormone (FSH) levels in women who had COVID-19." (PMID 40564856, 2025). "The main findings were: lower AMH levels, increased FSH levels, and higher testosterone and prolactin levels in women in the COVID-19 group, compared to the age-matched control group." (PMID 35055804, 2022). "In conclusion, the number of doses, time interval, and manufacturer of the inactivated COVID-19 vaccine did not affect AMH levels in Chinese women." (PMID 40535340, 2025). "This study demonstrated that the COVID-19 inactivated vaccine did not affect AMH levels in Chinese women from the number of doses, the manufacturer and the time interval after vaccination." (PMID 40535340, 2025). "Therefore, the current study aimed to assess the menstrual disorder and the AMH, TSH, TPO, and prolactin levels in female patients with COVID-19." (PMID 39906086, 2024). "The average sex hormone and Anti-Müllerian hormone (AMH) concentrations of women of childbearing age with COVID-19 were not different from those of age-matched controls." (PMID 39791609, 2024). "Endocrine dysfunction in the form of low AMH and high TSH were common among COVID-19 patients." (PMID 39906086, 2024). "Within this cohort, 70 patients demonstrated no change in mean (SD) AMH levels measured before (3.83 [4.56] ng/mL) and after (3.86 [4.31] ng/mL) COVID-19 vaccination (95% CI, 0.491-0.566; P = .89)." (PMID 37326996, 2023).
COVID-19 (continued). "In our study, we observed that basal follicle-stimulating hormone (FSH) levels were lower and AFC was higher in the COVID-19 group compared to the non-COVID-19 group, while AMH levels were similar between both groups." (PMID 38348053, 2023). "Anti-müllerian hormone (AMH) and estradiol are markers of high ovarian reserve and have been shown to negatively correlate with severity of COVID-19, independent of age, suggesting that pre-menopausal women are somewhat protected against severe COVID-19." (PMID 34506535, 2021). "The COVID-19 virus does not affect AMH, a measure of ovarian reserve." (PMID 38738039, 2024).
metabolic syndrome (14 papers, 2013 to 2025). A cluster of metabolic risk factors for CARDIOVASCULAR DISEASES and TYPE 2 DIABETES MELLITUS. "The investigators evaluated the relationship between AMH and 25OH-D and the metabolic syndrome (MetS) risk in 291 healthy, late-reproductive-age (35–49 years) women with regular menstrual cycles." (PMID 32481491, 2020). "Low AMH in younger adults has also been associated with metabolic syndrome." (PMID 23940675, 2013). "Further research will be needed to evaluate the relationship of AMH levels with lipid profiles and metabolic syndromes and to evaluate AMH as a tool for monitoring the success of PCOS treatment." (PMID 25119192, 2014). "3.Promoting women’s health: The application of age-related AMH screening criteria can help detect and intervene in PCOS early, improve patients’ quality of life and reproductive health, and reduce the risk of long-term complications such as metabolic syndrome and cardiovascular disease." (PMID 40597965, 2025). "AMH levels different between those with and without metabolic syndrome, with a mean difference of 0.085 (95% CI: 0.035 to 0.134)." (PMID 40713717, 2025).
persistent Müllerian duct syndrome (14 papers, 2014 to 2024). "The first SNP identified is a “probably damaging” heterozygous missense variant (Polyphen) in exon 3 of the AMH gene (c.482G>A) and is associated with persistent Müllerian duct syndrome." (PMID 35995809, 2022). "In patients with DSD, serum AMH levels are commensurate with the amount of testicular tissue, except for those with a Persistent Müllerian duct syndrome due to AMH mutations." (PMID 35712256, 2022). "Finally, in boys with a persistent Müllerian duct syndrome, undetectable or very low serum AMH suggests a mutation of the AMH gene, whereas normal AMH levels orient toward a mutation of the AMH receptor." (PMID 33013698, 2020). "An extremely rare exception is the Persistent Müllerian Duct Syndrome caused by AMH gene mutations, which may explain the finding of undetectable serum AMH in a boy with abdominal testes." (PMID 27799946, 2016). "Where there is a mutation in the AMH gene, or in AMHR2, Persistent Müllerian Duct Syndrome (PMDS) occurs." (PMID 35909548, 2022). "The persistent Müllerian duct syndrome (PMDS) is the only example of DSD due to an isolated defect of AMH synthesis or action." (PMID 33013698, 2020). "Yet, low sequence divergence, as little as one amino-acid changing SNP, was shown to be sufficient to impact the signal transduction function of the human AMH protein, leading to persistent Müllerian duct syndrome." (PMID 31437150, 2019). "The AMH gene was sequenced in a single case with the clinical diagnosis of persistent Müllerian duct syndrome." (PMID 25248670, 2014). "AMH is not detectable in serum; however, ultrasound examination should be performed to rule out persistent Müllerian duct syndrome (PMDS) due to an AMH mutation." (PMID 33013698, 2020). "Persistent Mullerian duct syndrome (PMDS) is typified by AMH either not being secreted or being inactive, which occurs as either a result of mutations in the activation of AMH or its receptor, AMHR2." (PMID 39368309, 2024).